HIF1A (hypoxia inducible factor 1 subunit alpha)
Diseases named in the same sentence as HIF1A in open-access papers (continued):
Sharing a sentence is not in itself a finding about the gene and the disease.
tumor (continued). "Strikingly, neutrophil-specific deletion of HIF-1α (HIF-1αΔNφ) significantly reduced tumor burden and improved overall survival in orthotopic transplanted mice, by converting the pro-tumorigenic neutrophil phenotype to an anti-tumorigenic phenotype." (PMID 36614196, 2023). "In the attempt to target hypoxia and restrain tumor angiogenesis, we have shown that zinc chloride induces HIF-1α protein degradation and inhibits the HIF-1-induced transcription of VEGF and angiogenesis, in vitro and in animal studies." (PMID 36900356, 2023). "While the deletion of the HIF1A gene reduces tumor vascularization and growth, the deletion of HIF2A, conversely, enhances angiogenesis with the formation of immature vessels and an increase in the degree of tumor hypoxia." (PMID 38003931, 2023). "HIF-1α inhibition combined with gemcitabine has led to reduced tumor growth and anti-tumor immunization in these preclinical studies (discussed in Section 5.3)." (PMID 36831579, 2023). "The oxidation and phosphorylation of PKM2 result in its nuclear localization and interaction with HIF-1α, which causes EMT-related molecules’ expression and increases tumour cell invasion." (PMID 37108242, 2023). "Accordingly, Hif-1α stabilisation is able to rescue both the expression of glycolysis-related genes and tumour cells’ viability induced by B-raf inhibition." (PMID 37198319, 2023). "In a hypoxic environment, tumour cells activate hypoxia-inducible factor 1α (HIF-1α) to reprogramme their energy metabolism pathways to maintain high proliferation rates and promote tumour growth, invasion and neointima formation." (PMID 37965452, 2023). "HIF2α is necessary for the growth of ccRCC xenografts, whereas knockdown of HIF1α enhances xenograft tumor formation in cell lines expressing both HIF1α and HIF2α." (PMID 37190141, 2023). "Plentiful studies dealing with the diverse genes targeted by HIF-1α-induced miR-210 overexpression have displayed its vast involvement in tumor proliferation, apoptosis, angiogenesis, invasiveness, and treatment resistance." (PMID 36939902, 2023). "The adaptive responses activated by hif-1α can make the tumor more aggressive by accelerating tumor progression, invasion, and metastasis." (PMID 37534226, 2023). "The transcription factor hypoxia-inducible factor 1α (HIF-1α) is regarded as the master regulator of cellular adaptation to hypoxia supporting angiogenesis and the metabolic rewiring of tumours to a state which is less dependent on oxygen and nutrients." (PMID 37166494, 2023). "Downregulation of HIF1A in VHL mutant cells leads an increase in proliferation, suggesting that HIF1A acts as a tumor suppressor in ccRCC." (PMID 37489462, 2023). "Our data confirm that the tumor inflammatory microenvironment in vivo abnormally activates the Stat3/HIF-1α/BNIP3 signaling pathway in skeletal muscle, leading to excessive mitophagy, which disrupts the body's energy balance and ultimately leads to fatigue." (PMID 36814560, 2023). "Research has revealed that B cells from tumour‐bearing mice express increased levels of hypoxia‐inducible factor 1‐alpha (HIF‐1α) protein." (PMID 37830387, 2023). "HISLA restrained the interaction between PHD2 and HIF‐1α to accelerate the accumulation of HIF‐1α and the release of lactic acid from tumor cells, which in turn up‐regulated HISLA in macrophages as a positive feedback loop." (PMID 36599655, 2023). "Little work has been published on the differential role of hypoxia-dependent macrophage HIF-2α when compared to HIF-1α in the context of tumor biology." (PMID 37124241, 2023). "Increased expressions of HIF1α and HIF2α have been observed in multiple tumor types; however, the TFs have differing roles across distinct cell types." (PMID 38173713, 2023). "Specifically, we detected highly glycolytic HIF-1α + GLUT1+ infiltrating neutrophils in tumor tissue." (PMID 36614196, 2023). "VEGF is an important growth factor for tumor angiogenesis, and it is considered as a specific target of HIF-1α." (PMID 37064130, 2023).
tumor (continued). "analyze differences between the expression of HIF-1α in tumor and healthy renal tissue from patients diagnosed with ccRCC, 2)." (PMID 38273861, 2023). "HIF-1α plays a vital role in the formation of the TME (tumor microenvironment) via the regulatory gene of anaerobic respiration and angiogenesis." (PMID 37513529, 2023). "HIF1A is overexpressed in cancers with involvement in biological processes of tumor cell survival, angiogenesis, metastasis, and tumor therapy." (PMID 36994412, 2023). "As a feedback, tumor cells release factors like IL-12, IL-4, hypoxia-inducible factor (HIF)-1α, and HIF-2α to sustain the M2 TAM phenotype." (PMID 38258072, 2023). "Injection of HIF-1α targeting siRNAs decreased the tumor volume and increased sensitivity to chemotherapy in these in vivo models." (PMID 36846589, 2023). "Apparently, enhanced PHF6 expressions in MDA-MB-231 cells significantly promoted in vivo tumor growth in mice, which was further abolished by HIF1α/HIF-2α DKO." (PMID 36967443, 2023). "In summary, all the studies mentioned here put forth HIF-1α as a potential target to surpass CSC-driven tumor progression, metastasis, and chemoresistance." (PMID 36846589, 2023). "The previous studies have shown that the tumor oxygenation strategy cannot effectively inhibit the expression of HIF-1α, which induces tumor resistance to radiation." (PMID 37899463, 2023). "There was much lower VHL level but endowed with higher HIF1A, LEPTIN, UCP1 and phosphorylated HSL protein expression in tumour associated adipose tissue as well." (PMID 37620316, 2023). "Hypoxic microenvironmental conditions, as reflected by high expression of HIF1α were linked with poor TIL density in the tumor-invading front and in inner tumor areas." (PMID 36586079, 2023). "HIF-1α positively regulates PD-L1 levels, suggesting that HIF-1α and hypoxia-induced elevation of PD-L1 expression comprise a mechanism of immune evasion by tumor cells." (PMID 37047482, 2023). "As such, future work includes further interrogating the cancer–neutrophil crosstalk and the latter’s recruitment into the tumor to understand the effect of HIF-1α in tumorigenesis." (PMID 36614196, 2023). "Recent studies have reported that VBP1 performs tumor suppressor functions through multiple mechanisms such as HIF-1α degradation in a pVHL-dependent manner and as a co-chaperone in the correct folding of newly synthesized pVHL." (PMID 37201586, 2023). "The overexpression of TERT and HIF1A in clock KO cells points indeed to their clock-regulated expression and further emphasizes the importance of the clock in the cellular response to tumour promoting conditions." (PMID 37400829, 2023). "Hypoxia within the TNBC tumor microenvironment stabilizes the HIF-1α to decide the cancer cell fate, genetics, metabolism, immune response and clinicopathology." (PMID 37492478, 2023). "HIF-1α assumes a critical role in orchestrating tumor metabolism to respond to the increasingly hypoxic microenvironment." (PMID 37760940, 2023). "HIF1α is a pivotal transcription factor in the tumor angiogenesis process, with the lactylation of HIF1α enhancing the transcription of KIAA1199, further promoting angiogenesis in PCa." (PMID 38069225, 2023). "Tumor cells within hypoxic regions also express elevated levels of hypoxia-inducible factor alpha (HIF-1α), with three isoforms having been found in mammals." (PMID 36672326, 2023). "HIF-1α is a master regulator of the hypoxia-response process of tumor cells under hypoxic conditions." (PMID 36925652, 2023). "HIF-1α plays a key role in modulating many cellular processes such as angiogenesis, cell proliferation, invasion and tumor progression." (PMID 37175546, 2023). "In tumor progression, the expression of related genes of all VEGF isoforms, PlGF, FGF, PDGF, and Ang-1 can be up-regulated by HIF-1α to promote tumor angiogenesis or induce drug resistance." (PMID 37169756, 2023).
tumor (continued). "HIF-1α is an oxygen-dependent transcriptional activator that plays crucial roles in tumor angiogenesis and mammalian development." (PMID 37090737, 2023). "As with angiogenesis, microvascular hyperplasia and inflammation influence tumor expansion are controlled by HIF-1α and NF-κB, both of which are downregulated by CoQ10." (PMID 36319818, 2023). "The enrichment of these immune pathways implies a broader role for HIF2α, whilst HIF1α was enriched for pathways involved in the stimulation of anti-tumour immune responses." (PMID 37240301, 2023). "The tumor samples were used to evaluate the expression of HIF-1α, Nrf2, HO-1, cMyc, cyclin D1, mTOR, and STAT3." (PMID 37465088, 2023). "Insufficient oxygen delivery in these regions hampers oxidative phosphorylation, leading to cellular hypoxia in tumor and surrounding cells, and further stabilizing HIF-1α." (PMID 38026690, 2023). "Mechanistically, under hypoxic conditions, H2S induces the proliferation and migration of endothelial cells (ECs) and promotes tumour angiogenesis by increasing the expression of HIF‐1α and VEGF." (PMID 36478328, 2023). "On the other hand, metastatic ccRCC displayed strong HIF-1α staining compared to the primary tumour." (PMID 37174052, 2023). "High tumor blood flow (TBF) and blood velocity (|ⴎ|) perfusion parameters were significantly associated with high IHC HIF-1α values." (PMID 37894447, 2023). "HIF-1α enhances programmed death-ligand 1 (PD-L1) expression on myeloid-derived suppressor cells (MDSCs), macrophages, and tumour cells, impairing T-cell activation." (PMID 36859310, 2023). "HIF-1α is upregulated in many malignant tumors and reflects the tendency of tumor metastasis and poor prognosis." (PMID 38192642, 2023). "Expression of HIF-1α and CD133 are associated with tumour progression and LNM in adenocarcinoma cells and tumour tissues." (PMID 37841777, 2023). "This study demonstrated that everolimus inhibits tumor angiogenesis and lymphangiogenesis through the downregulation of HIF-1α within the tumor microenvironment." (PMID 36745547, 2023). "The transcription factor hypoxia-inducible factor 1α (HIF-1α) is a central mediator of tumor hypoxia." (PMID 38066600, 2023). "EMT genes like KRT19, CTNNB1 and TWIST1 and the hypoxia marker HIF1A were significantly changed in tumors, indicating altered tumor microenvironment." (PMID 37170215, 2023). "HIF-1α is the primary regulator of hypoxia response, inhibiting the tumor cells migration and preventing cancer progression." (PMID 37005437, 2023). "Our samples had more tumor necrosis present, which, by itself presents a strong hypoxia inducer, which is a plausible explanation for higher HIF-1α immunohistochemical expression." (PMID 38053655, 2023). "Stephen demonstrated that combined immunotherapy with respiratory hyperoxia can reduce tumor hypoxia and attenuate hypoxic/HIF‐1α/A2 adenosine immunosuppression, thereby exerting a powerful antitumor effect." (PMID 36703877, 2023). "HIF1α especially has long been a gene of interest as it is induced by both hypoxia and acidosis and plays a role in many aspects of tumor development." (PMID 36982873, 2023). "VEGF-C stimulates lymphangiogenesis by binding to VEGFR3 and HIF-1α has been shown to induce upregulation of VEGF-C in cancer tumours." (PMID 36994416, 2023). "In the present study, we confirmed that IP affects the tumor microenvironment, and this altered tumor microenvironment is significantly correlated with HIF-1α expression." (PMID 38012636, 2023). "This was associated with decreased S-palmitoylation and phosphorylation of STAT3 as well as HIF1α abundance in tumor lysates which is consistent with in vitro assay." (PMID 38051779, 2023). "The dysregulation of HIF1A in ccRCC contributes to the hypervascular nature of the tumor and its aggressive behavior." (PMID 38053655, 2023). "Hypoxic microglia infiltrating tumors promote tumor angiogenesis with HIF-1α-mediated upregulation of VEGF-A expression." (PMID 37700840, 2023).
tumor (continued). "Hypoxia-inducible factor 1α (HIF1A) is a major mediator of tumor physiology, and its activation is correlated with tumor progression, metastasis, and therapeutic resistance." (PMID 37311884, 2023). "Based on these results, expression levels of BIRC5, HIF1A, and FLT4 associated with primary NSCLC tumor progression and metastasis were compared to normal samples." (PMID 37509650, 2023). "Elevated NO levels, in turn, promote the expression of certain vascular growth factors (e.g., VEGF, HIF1α), ultimately driving tumor angiogenesis." (PMID 38069225, 2023). "Cancer cells also used activation of HIF-1α to increase glucose uptake and glycolysis flux, promoted glucose catabolism and adapted to low oxygen environment to ensure tumor growth." (PMID 37663261, 2023). "As a transcription factor, HIF1A is implicated in various biological activities, such as angiogenesis, glucose metabolism, cell proliferation, survival, and apoptosis; HIF1A can also promote tumor cell migration in different tumors." (PMID 37848931, 2023). "It was proposed that inhibition of tumor angiogenesis and progression can be achieved by reducing the expression of HIF-1α, a downstream factor that is suppressed when oxygen levels are increased." (PMID 37569531, 2023). "Overexpression of HIF-1a in several cancers is relevant to angiogenesis, cell proliferation and survival, and accelerated tumor malignancy." (PMID 37287062, 2023). "HIF-1α immunofluorescent expression in primary tumors was compared between the clinical characteristics of patients, tumor stage, and histological subtype." (PMID 37445752, 2023). "Tumor hypoxia induces stabilization of the transcription factor hypoxia-inducible factor 1-alpha (HIF-1A), which drives transcriptional responses in both immune cells and cancer cells, thus influencing tumor development." (PMID 37443711, 2023). "The deletion of KLF5 enhances tumor angiogenesis by dampening PI3K/AKT signaling in PTEN-deficient PCa cells, leading to an accumulation of HIF1α." (PMID 38069225, 2023). "Meanwhile, the level of PYCR1 pY135 was shown to correlate with HIF-1α levels in mice tumor tissues." (PMID 37777542, 2023). "The VHL protein (pVHL) functions as a tumor suppressor by regulating the degradation or activation of protein substrates such as HIF1α and Akt." (PMID 36813923, 2023). "The letrozole inhibited PD-L1 expression in tumor cells, boosted tumor perfusion, promoted vascular normalization, and downregulated HIF-1α in CT26 and MC38 tumor." (PMID 37055842, 2023). "Under conditions of hypoxia, cancer cells with hypoxia inducible factor-1α (HIF-1α) from heterogeneous tumor cells show greater aggression and progression in an effort to compensate for harsh environmental conditions." (PMID 37777750, 2023). "This formulation acts as an antioxidant which significantly reduced the level of ROS that destabilizes the hypoxia-inducible factor-1α (HIF-1α) and consequently, tumour size was decreased in the mice model." (PMID 38112935, 2023). "HIF1α is upregulated due to hypoxia brought about by the tumor microenvironment, which results in the upregulation of HK2, making HK2 the most highly expressed HK in multiple tumors." (PMID 37109475, 2023). "Downregulation of HIF-1a signaling within the tumor itself can also allow for enhanced immune activity." (PMID 36980629, 2023). "TIL density in inner stroma was inversely linked to local invasion (marginal p = 0.05), tumor budding (TB) (p = 0.005), MIB1 (p = 0.02), and HIF1α expression (p = 0.02)." (PMID 36586079, 2023). "Many studies have suggested that HIF-1α can inhibit tumour growth while HIF-2α promotes tumour growth and metastasis." (PMID 38136342, 2023). "In human solid tumors, the intrahypoxia region accounts for 19% to 70% of the tumor volume; thus, adaptation to hypoxia via the induction of HIF-1α is essential for cell survival and function." (PMID 36707659, 2023).
tumor (continued). "Significantly, HIF1α proteins bind to CDCA8 promoter for transcriptional activation, forming a positive-feedback loop to sustain BCa tumor cells under oxygen-deficient environment." (PMID 37813876, 2023). "Hypoxia-inducible factor alpha (HIF-1α) is a key gene that regulates the metabolic mode of tumor cells." (PMID 37646027, 2023). "Immune cells recruited to the hypoxic tumor microenvironment from the oxygen-rich bloodstream up-regulate HIF-1α expression." (PMID 36614196, 2023). "High levels of HIF-1α are expressed in many cancers, and they correlate with tumor growth and migration." (PMID 36334237, 2023). "HIF-1α has also been identified as the core factor of the hypoxia signaling pathway, which is involved in tumor angiogenesis, proliferation, invasion, metastasis, and even tumor immune suppression." (PMID 36675491, 2023). "Around necrotic foci in GBM, HIF-1α concentrates in tumor cell nuclei, whereas in low-grade gliomas (e.g. anaplastic astrocytoma) it is mostly found in cytoplasm." (PMID 37542119, 2023). "We demonstrated that HIF-1α is expressed at higher levels in OSCC tissues than in adjacent non-tumor tissues." (PMID 37095487, 2023). "As a proof of principle, HIPK2 silencing with small interfering RNA upregulated HIF-1α in cancer cells, inducing a pseudohypoxic tumor phenotype in normoxic conditions, fueling tumor progression, and chemoresistance." (PMID 36900356, 2023). "Using human ccRCC cell lines, it has been reported that HIF-1α is essential for tumor formation and induces a glycolytic profile, while HIF-2α regulates lipoprotein metabolism, biogenesis of ribosome, and induction of MYC and E2F." (PMID 35565420, 2022). "MiR-519c can target HIF-1α and reduce the expression of HIF-1α protein, thereby reducing tumor angiogenesis in NSCLC." (PMID 35918758, 2022). "Under hypoxic condition, hypoxia-inducible factor 1α (HIF-1α) has been regarded as the primary regulator facilitating angiogenesis by upregulating pro-angiogenic genes in tumor cells, such as VEGF." (PMID 36234977, 2022). "While the development of a solid cancer depends on the supply of oxygen and nutritional status, pVHL functions to maintain HIF-1α at low levels and suppress neovascularization, thereby acting as a tumor suppressor." (PMID 36234722, 2022). "The results showed that tumor volume and weight were decreased with HIF1α or HIF2α knockout, and the group with simultaneous HIF1α and HIF2α knockout presented the smallest tumor volume and weight." (PMID 34976166, 2022). "Similar to iNOS, COX-2/PGE2 and HIF-1α pathways have been suggested to favour tumour-promoting inflammation by mechanisms that include direct inhibition of cytotoxic cell infiltration and effector function." (PMID 35660630, 2022). "In a mouse model of human B cell lymphoma implanted subcutaneously, oral treatment of ascorbic acid (5 g/L) reduced HIF1α expression and prevented tumor development." (PMID 36203466, 2022). "HIF-1α regulates the biological behavior of tumors by mediating tumor metabolism by inducing glycolysis." (PMID 35896535, 2022). "Studies have reported that the up-regulated immune checkpoint PD-L1 in tumor cells presents HIF-1α dependence, promote the apoptosis of cytotoxic T cells, and participate in the immune escape of tumor cells." (PMID 36212414, 2022). "This review discusses the current knowledge of how hypoxia and HIFs facilitate tumor immune escape, with evidence to date implicating HIF1A as a molecular target in such immune escape." (PMID 35659268, 2022). "Hypoxia, controlled by transcription factor hypoxia-inducible factor-1α (HIF-1α), plays important roles in the pathobiology of inflammation and pathology, including regulation of tumor progression." (PMID 35355718, 2022). "The knockdown of Nrf2 expression inhibited the invasion capacity of tumor cell under hypoxic conditions and suppressed the expression of Nrf2, heme oxygenase-1 (HO-1) and HIF-1α." (PMID 35417854, 2022).